IL3 (interleukin 3)
Diseases named in the same sentence as IL3 in open-access papers (continued):
Sharing a sentence is not in itself a finding about the gene and the disease.
parasitic infections (12 papers, 2015 to 2025). "Previous studies had found that parasitic infections led to an increase in inflammatory factors (IL-3 and IL-6) in sheep." (PMID 40007749, 2025). "Parasite density was the principal predictor of the cytokine levels, as parasitemia positively associated with IL‐10, GM‐CSF, IL‐6, IL‐1β, IFN‐ɣ, and TNF‐α, but negatively associated with IL‐3 and TGF‐β." (PMID 39240033, 2024). "By 8 days PI, parasitemia in Mcpt4-/- mice was correlated mainly with type-2 cytokines including large fold-changes in IL-3 and IL-10, which were also notable in Mcpt4+/+ mice." (PMID 35154114, 2022). "At day 4 p.i. in baso (−) mice, 16S copy numbers were directly and weakly negatively correlated with plasma IL-2 and IL-3, whereas parasitemia was weakly correlated with plasma MCP-1 (negatively) and ileal MIP-1α (positively)." (PMID 35970557, 2022). "In baso (+) mice at day 3 p.i., parasitemia was directly and negatively correlated with plasma IL-1β and IL-3, whereas MIP-1β was directly and strongly positively correlated with gametocytemia." (PMID 35970557, 2022). "During parasitic infections, the increase in the number of peripheral blood is driven by Th2-derived cytokines, i.e., IL-5, IL-3." (PMID 28620263, 2017). "KEGG enrichment analysis again enriched various pathways, including “Signaling by CSF3 (G-CSF),” “RHO GTPases Activate NADPH Oxidases,” “Regulation of signaling by CBL,” “Parasite infection,” “Neutrophil degranulation,” “Leishmania phagocytosis,” “Leishmania infection,” “Interleukin-3." (PMID 38629070, 2024). "The following factors may be related to the high variation in parasitemia, i.e. genetic background of the donor, the quality of the hematopoietic stem cells, the efficiency of the hydrodynamic injection and therefore the IL-3/EPO expression." (PMID 26098918, 2015). "This was attributed to the activation of the inflammatory cascade induced by parasitic infection, and TNF-α stimulated the production of inflammatory cytokines (IL-3, IL-6, and IL-10)." (PMID 40007749, 2025). "Participants with high parasitemia had raised TNF‐α (p < .001), IFN‐ɣ (p < .001), IL‐1β (p < .001), IL‐6 (p < .001), GM‐CSF (p < .001), and IL‐10 (p < .001), but reduced IL‐3 (p < .001) and TGF‐β (p < .001) than those with low parasitemia." (PMID 39240033, 2024). "However, the characterization of IL-3-deficient mice affirmed IL-3 is not essential for the generation of mast cells under physiological conditions but contributes to the increase of mast cells in the presence of parasitic infection." (PMID 37296626, 2023). "However, plasma levels of IL‐3 and TGF‐β were lower among participants with high parasitemia than among those with parasite density less than 10000 parasites/μL." (PMID 39240033, 2024). "In contrast, oocysts were absent from the baso (+) network, parasitemia was negatively correlated with plasma IL-3 and IL-1β, and gametocytemia was strongly positively correlated with plasma MIP-1β at 3 d p.i.." (PMID 35970557, 2022). "In the present study, we demonstrated for the first time that IL-3-producing CD4+ memory T cells, including TRM cells, play an essential role in the basophil recruitment to the site of tick re-infestation and, thereby, contribute to the acquired protective immunity against tick infestation." (PMID 29085376, 2017). "Therefore, the requirement of IL-3 produced by CD4+ T cells appears to be common to the basophil recruitment to draining lymph nodes and skin in the parasitic infections, in spite of the difference in the timing of recruitment." (PMID 29085376, 2017).
breast carcinoma (11 papers, 2014 to 2025). "The autocrine loop of IL-6/IL-8 and IL-3 is well documented and provides evidence about the distinct response among different breast cancer subtypes." (PMID 41373619, 2025). "Clinical studies related to breast cancer have revealed that honey is effective in increasing blood cell counts, interleukin-3 levels, and quality of life." (PMID 36978815, 2023). "Th2 cell–induced terminal differentiation is driven by IL-3/IL-5/GM-CSF binding to receptors with a common β chain on breast cancer cells, which results in the activation of the signaling transducer and activator of transcription 5 (STAT5) pathway." (PMID 35657353, 2022). "In conclusion, c-Kit+ ASCs can promote the tumor angiogenesis and growth of breast cancer by recruiting EPCs via a synergistic effect of c-Kit and IL-3." (PMID 28573141, 2017). "Furthermore, IL-3, which can also be secreted by breast cancer cells, promotes the upregulation of the oncogenic miR-155-5p, thereby impairing the function of the β-catenin destruction complex." (PMID 41373619, 2025). "Importantly, Th2 cell immunity, facilitated by the release of interleukin 3 (IL-3), interleukin 5 (IL-5), and granulocyte-macrophage colony-stimulating factor (GM-CSF), induces terminal differentiation in developing breast cancer." (PMID 39507526, 2024). "Next, we examined the effector function of IL-3 in Th2 cell immunity against breast cancer." (PMID 35657353, 2022). "Taken together, our results suggest that c-Kit may stimulate the proliferation of 4T1 breast cancer cells by promoting IL-3 release." (PMID 28573141, 2017). "c-Kit+ ASCs may promote breast cancer growth and angiogenesis by a synergistic effect of c-Kit and IL-3." (PMID 28573141, 2017). "We found that c-Kit+ ASCs had an intrinsic proangiogenic capability and stimulated IL-3 release, which could promote the proliferation of 4T1 breast cancer cells or the growth of mature adipose cells." (PMID 28573141, 2017). "STAT5 is phosphorylated in endothelial cells treated with IL-3, which suggests an involvement in angiogenesis and cell motility, and it is therefore also possible that IL-3 may play a role in breast cancer cells." (PMID 24913037, 2014). "We show that IL-3, IL-5, and GM-CSF released by Th2 cells are responsible for the induction of terminal differentiation in the developing breast cancer and demonstrate that Th2 cell immunity reverted high-grade breast cancers into low-grade, fibrocystic-like structures." (PMID 35657353, 2022). "In addition, we found positive correlations between TSLP expression and CSF2/IL3/IL5 and differentiation genes expression in human breast cancer." (PMID 35657353, 2022). "A role for IL-3 in breast cancer has not yet been established." (PMID 26361584, 2015). "Furthermore, the specific role of IL-3 and IL-5 versus GM-CSF to breast cancer suppression and the contributions of antigen-nonspecific T cell response and other immune cell types including eosinophils, macrophages, and CD8+ T and NK cells to Th2 cell immunity warrant further investigation." (PMID 35657353, 2022).
Alzheimer disease (10 papers, 2018 to 2025). A progressive, neurodegenerative disease characterized by loss of function and death of nerve cells in several areas of the brain leading to loss of cognitive function such as memory and language. "However, the JAK2-STAT5 signaling pathway mediates interleukin-3-induced activation of microglia, which is associated with the pathogenesis of multiple sclerosis, Alzheimer’s disease (AD) and Parkinson’s disease." (PMID 30194287, 2018). "In Alzheimer’s disease (AD) patients, decreased α-tocopherol levels were associated with elevated inflammatory cytokines (G-CSF, GM-CSF, INF-α2, IL-3, IL-17, and IL-8) and reduced levels of several exosomal microRNAs (miR-122, miR-21, miR-132)." (PMID 40650110, 2025). "Astrocyte-derived IL-3 binds specific receptors on the surface of microglia in Alzheimer’s disease (AD)." (PMID 37762511, 2023). "In Alzheimer’s disease brains, IL-3 ameliorates Alzheimer’s disease pathology and cognitive dysfunction, while promoting microglial motility." (PMID 35968363, 2022). "A total of 311 participants with cerebrospinal fluid (CSF) IL-3, soluble triggering receptor expressed on myeloid cells 2 (sTREM2), and AD biomarkers were included from the Alzheimer’s disease Neuroimaging Initiative (ADNI)." (PMID 36578067, 2022). "IL3 was reported to be one of the 5-protein biomarker molecular signature for predicting Alzheimer’s disease." (PMID 32138265, 2020). "Although correlations have been drawn linking IL‐3 to the pathophysiology of experimental autoimmune encephalomyelitis, multiple sclerosis, and Alzheimer's disease, the precise function of IL‐3 within CNS injury, particularly in the context of SCI, remains largely unexplored." (PMID 39697159, 2024). "Additionally, in Alzheimer's disease, astrocytic IL‐3 activates microglia through the IL‐3Rα receptor, initiating the clearance of β‐amyloid and tau aggregates." (PMID 39697159, 2024). "For instance, neurotoxic reactive A1 astrocytes can be induced by activated microglia 31, astrocytes remove cell debris when microglial phagocytic activity is impaired 32, and microglia can be reprogrammed by astrocyte-derived interleukin-3 (IL-3) to ameliorate the pathology of Alzheimer's disease." (PMID 35673563, 2022).
lymphoma (10 papers, 2009 to 2025). A malignant (clonal) proliferation of B- lymphocytes or T- lymphocytes which involves the lymph nodes, bone marrow and/or extranodal sites. "Another explanation for the MC-promoting effect of NPM-ALK would be that malignant cells in the NPM-ALK-induced lymphomas produced cytokines that induced MC growth, such as IL-3 or IL-4." (PMID 21297223, 2010). "We have shown that mouse macrophages display a pro-inflammatory response to Ba/F3 lymphoma cells dying by apoptosis associated with autophagy in response to IL-3 withdrawal, but not when they are exposed to living, apoptotic, necrotic or necrostatin-1-treated cells." (PMID 22768222, 2012). "The identification of IGH::IL3 fusions in B-LL further proved the unique capacity of GPM to detect promoter/enhancer juxtapositions that cannot be captured by RNA sequencing, as noted in mature lymphomas." (PMID 41374977, 2025).
multiple sclerosis (9 papers, 2018 to 2025). A progressive autoimmune disorder affecting the central nervous system resulting in demyelination. "IL-3 levels are also increased in the cerebrospinal fluid (CSF) of multiple sclerosis (MS) patients, and its association with human relapsing-remitting MS (RRMS) exacerbates spinal cord inflammation, demyelination, and clinical severity in experimental autoimmune encephalomyelitis (EAE)." (PMID 38702781, 2024). "IL-3, known to promote EAE development, has been implicated in glial-peripheral immune crosstalk in multiple sclerosis." (PMID 40399986, 2025). "Although IL‐3 has been extensively studied for its cytokine functions, recent investigations have unveiled the IL‐3/IL‐3Rα signaling pathway as a mediator of astrocyte–macrophage communication, exacerbating conditions such as multiple sclerosis." (PMID 39697159, 2024). "Furthermore, in transgenic mice, IL-3 was indispensable for generating multiple sclerosis (MS)-like disorders in brain macrophages, and neurological dysfunction were observed in mice expressing antisense IL-3 RNA." (PMID 37450927, 2024). "Little is known about the role of IL-3 in ischemic stroke; however, it is produced by activated CD4+/CD8+ T cells and has been implicated in the development of neuroinflammatory conditions such as multiple sclerosis." (PMID 33376583, 2020).
prostate carcinoma (9 papers, 2013 to 2023). A carcinoma that arises from epithelial cells of the prostate gland. "The level of IL-3 has been correlated with fatigue in patients with prostate cancer who were receiving radiotherapy." (PMID 32707913, 2020). "In this study, the cell stemness influence of a group of interleukins including IL-3, 6, 10, 11 and 24 on human prostate cancer cell lines LNCaP and PC-3 was explored in vitro." (PMID 26528857, 2015). "Our study reveals another aspect of IL-3 functions, namely stimulating the stemness of prostate cancer cells." (PMID 26528857, 2015). "In the current study, we investigated whether intratumoral expression of murine IL-3 (mIL-3) enhances the anti-tumor effect of the HSV-tk/GCV system in a murine TRAMP-C1 prostate cancer model in vivo." (PMID 23441198, 2013). "In this study, we demonstrate that bicistronic expression of IL-3 and HSV-sr39tk/GCV suicide gene system exerts a synergistic effect inhibiting the growth of TRAMP-C1 prostate cancer cells in vivo, but not in vitro." (PMID 23441198, 2013).
systemic lupus erythematosus (9 papers, 2015 to 2024). An autoimmune multi-organ disease typically associated with vasculopathy and autoantibody production. "In the Lyn-deficient mouse model of lupus, IL-3-responsive progenitor cells are elevated in spleen, and IL-3 induces enhanced signaling and survival of Lyn−/− plasma cells, suggesting it may play a role in the support of autoreactive plasma cells." (PMID 26579125, 2015). "IL-3 is known to potently activate basophils, its production by T cells is known to be upregulated in SLE patients’ blood as well as in lupus-like mouse models and SLE patient IL-3 signature is associated with CD274 (PD-L1) gene upregulation in whole blood." (PMID 38649353, 2024). "Recent studies have shown that circulating NET levels are increased in systemic lupus erythematosus (SLE) for a functional block of NET removal mediated by anti-DNase antibodies or, in rare cases, by DNase IL3 mutations." (PMID 33829021, 2021). "We next assessed whether IL-3 or IL-4 blockade could modulate in vivo the PD-L1 expression on the surface of basophils in the lupus-like context of Lyn–/– mice." (PMID 38649353, 2024). "Addition of IL-3 to splenocytes ex vivo increased PD-L1 expression on the surface of basophils as did FcεRI crosslinking suggesting that these signals may contribute to PD-L1 overexpression on basophils in the lupus context." (PMID 38649353, 2024). "Finally, administration of exogenous IL-3 or an anti-IL-3-blocking antibody to MRL/lpr mice (which develops a spontaneous autoimmune disease that resembles human systemic lupus erythematosus) has shown a prominent role for IL-3 in the pathogenesis and progression of lupus nephritis." (PMID 30769926, 2019). "Altogether, these results strongly suggest that the increased IL-3 and IL-4 titers sustain basophil activation and accumulation in SLO in the lupus-like context where they promote their PD-L1 and IL-4-dependent effects on TFH cell and plasmablast accumulations." (PMID 38649353, 2024).
Thrombocytosis (9 papers, 2017 to 2025). Increased numbers of platelets in the peripheral blood. "The production of hepatic thrombopoietin and subsequent thrombocytosis is caused by elevated levels of thrombopoietin-inducing cytokines, such as interleukin-1 (IL-1), IL-3, IL-11, and tumor-derived IL-6, in tumor-host tissues." (PMID 39941717, 2025). "Production of thrombopoietic cytokine in liver and thrombocytosis are caused by interleukin-1 (IL-1), IL-3, IL-4, IL-11, and tumor-derived platelet factor 4 in tumor host tissues." (PMID 35268446, 2022). "The proinflammatory cytokines released in cancer, such as interleukins IL-1, IL-3, and IL-6, can promote the proliferation of megakaryocytes and increase the presence of large platelets, causing their activation and aggregation and possibly leading to the gradual establishment of thrombocytosis." (PMID 36975471, 2023). "The release of proinflammatory mediators such as interleukin (IL)-1, IL-3, and IL-6 enhances megakaryocyte proliferation and results in thrombocytosis." (PMID 39831170, 2025). "The release of cytokines such as IL-1, IL-3 and IL-6 in the proinflammatory phase can stimulate the activation of megakaryocytes, which results in thrombocytosis." (PMID 29383181, 2017). "Increasing numbers of studies suggested that the proinflammatory cytokines released by tumors, like interleukin-1 (IL-1), interleukin-3 (IL-3), and interleukin-6 (IL-6), can promote megakaryocyte proliferation, and lead to thrombocytosis gradually." (PMID 29179480, 2017).
autoimmune disease (8 papers, 2016 to 2024). A disorder resulting from loss of function or tissue destruction of an organ or multiple organs, arising from humoral or cellular immune responses of the individual to their own tissue constituents. "Dysregulation of the IL-3/STAT5 signaling have been associated with inflammatory and autoimmune diseases characterized by inflammatory cell infiltration and organ damage." (PMID 38702781, 2024). "Interleukin-3 (IL-3), a multifunctional cytokine involved in astrocyte–microglia communication, is believed to involve in inflammatory and autoimmune diseases." (PMID 36578067, 2022). "GM-CSF and IL-3 also modulate the effector functions of several mature immune cell subsets and have been shown to play a role in inflammatory and autoimmune diseases." (PMID 28138327, 2016). "Given the central role of GM-CSF and IL-3 in inflammatory and autoimmune diseases, our results provide important information to understand mechanisms of monocyte activation in such disorders and prompt their investigation in vivo." (PMID 28138327, 2016). "In particular, GM-CSF and IL-3 exert a significant control on monocyte and macrophage effector functions, as assessed in experimental models of inflammatory and autoimmune diseases and also in human studies." (PMID 28138327, 2016). "Several studies have reported a prominent role for GM-CSF and to a lesser extent IL-3 in autoimmune diseases, and for some of them such as multiple sclerosis (MS) and rheumatoid arthritis (RA), humanized blocking antibodies are now being evaluated in clinical trials." (PMID 30769926, 2019).
colitis (8 papers, 2021 to 2024). Inflammation of the colon. "In inflammatory bowel diseases (IBD), the influence of IL-3 varies based on the degree of intestinal inflammation, which provides protective effects at the initiation of colitis but becomes detrimental during acute colitis." (PMID 38702781, 2024). "Therefore, tissue‐prevalent mast cells stimulated by a combination of IL‐3 and IL‐33 would secrete high levels of IL‐6, but not IL‐2, and represent potential mediators of the negative regulatory role of IL‐3 in colitis‐mediated immune responses by induction of RORγt+ Tregs." (PMID 33427298, 2021). "The present study confirmed and extended this effect by detecting a substantial reduction of IL-1α, IL-1β, IL-6, TNF-α, INF-γ, G-CSF, IL-13, GM-CSF, IL-3, MIP-1α, RANTES, and eotaxin cytokines in response to UTA77 treatment in both colitis models." (PMID 34497514, 2021). "The elevated levels of IL-1α, IL-1β, IL-3, IL-6, IL-9, IL-12 (P40), IL-12 (P70), IL-17, GM-CSF, and G-CSF in response to DSS treatment in the current study, supports the strong involvement of macrophage activation in the DSS induced colitis model." (PMID 36365201, 2022).